MMP9 (matrix metallopeptidase 9)
Diseases named in the same sentence as MMP9 in open-access papers (continued):
Sharing a sentence is not in itself a finding about the gene and the disease.
colon carcinoma (continued). "Given abnormal levels of MMP9, MMP12 and TIMP3 mRNA expression in tumors from CRC patients and controls, we next measured the level of the MMPs and TIMP3 proteins in human colon cancer epithelial cells compared to normal colon cells by immunoblot." (PMID 32171282, 2020). "Silencing HOTAIR elevates E-cadherin expression and suppresses that of vimentin and MMP-9, which can lead to EMT in colon cancer cells." (PMID 33246471, 2020). "Flavanol extract from Chaenomeles japonica, a Japanese fruit, inhibited COX-2, matrix metalloproteinase-9 (MMP-9), and NF-kB expression indicating a cytotoxic anti-inflammatory and anti-metastatic activities toward the colon cancer SW-480 cells." (PMID 31031748, 2019). "miR-340 treated colon cancer cells expressed significantly less MMP-2 and MMP-9 than pCMV treated cells." (PMID 29435169, 2018). "Of these, six mRNA including ECM1, GZMB, KLK10, CCL20, MMP9, and IL7 have been previously reported to have a prognostic role in colon cancer." (PMID 29377588, 2018). "However, vanin-1 deficiency may also reduce colon cancer development by down-regulating several mediators of inflammation in intestinal epithelial cells that promote colorectal carcinogenesis and that are overexpressed in tumors, as COX-2, iNOS and MMP9." (PMID 28448444, 2017). "It specifically inhibited the metastatic dissemination capability of colon cancer cells HT29, including the migration and invasion ability, and their adhesion to human endothelium through inhibiting integrin αvβ6, MMP-2, MMP-9, and ERK phosphorylation by HT29." (PMID 28634392, 2017). "Knockdown of OPN expression in human colon cancer cells suppresses cell proliferation, adherence, invasion, and expression of angiogenetic factors, such as VEGF, MMP-2, and MMP-9." (PMID 28505114, 2017). "However, vanin-1 deficiency may also limit the development of colon cancer by down-regulating several mediators of inflammation in intestinal epithelial cells that promote colorectal carcinogenesis and are overexpressed in tumor as COX-2, iNOS and MMP9." (PMID 28448444, 2017). "MMP9 mRNA, protein level and activity are increased in human and animal models of CRC and potentiate colon cancer metastasis." (PMID 27861153, 2017). "Our results indicate that C3G silencing-mediated p38α hyperactivation increases MMP2 and MMP9 activities in MEFs and HCT116 colon carcinoma cells, which correlates with the effect on cell migration and invasion." (PMID 27286263, 2016). "When colon cancer cells were treated with 20, 40 and 60 μmol/L NCTD for 24 h, the activity of MMP-3 and MMP-9 decreased substantially in a dose-dependent manner." (PMID 26846153, 2016). "1α,25(OH)2D3 also inhibited the secretion of MMP-2 and MMP-9 and increased expression of F-actin induced by TGF-β1/β2 in colon cancer cells." (PMID 27548154, 2016). "Matrix metalloproteinases (MMPs) produced by TAMs, such as MMP9 and MMP2 are required for the tumor cell invasion in colon cancer." (PMID 26799669, 2016). "CCL9 (and CCL15) secreted by mouse and human colon cancer cells has been shown to recruit immature myeloid cells (iMCs), which produce matrix metalloproteinases MMP2 and MMP9 required for successful colonization of the liver." (PMID 25882816, 2015). "SCF was required for migration and invasion of human colon carcinoma cells DLD-1 through reconstituted basement membranes and up-regulated matrix metalloproteinase (MMP)-9 activity." (PMID 24721839, 2014). "In colon cancer, over-expression of p38 gamma MAPK was shown to lead to increased c-Jun synthesis, resulting in enhanced MMP-9 transcription and MMP-9-dependent invasion." (PMID 24518611, 2014). "Although MMP9 was detected in some CTHRC1-negative patients, CTHRC1 was expressed in most colon cancer patients, and CTHRC1-positive tissues expressed MMP9." (PMID 24504172, 2014).
colon carcinoma (continued). "Several drugs such as goniothalamin and 17β-estradiol were reported to inhibit the migration of lung and colon cancer cells by attenuating MMP-2 and MMP-9 activities, respectively." (PMID 23710144, 2013). "In colon cancer, a study suggests that CCR7 promotes metastasis by upregulating matrix metalloproteinase-9 (MMP-9) expression." (PMID 24259307, 2013). "The effect of IL-1β and IP6 on the expression of mRNA of MMP-1, MMP-2, MMP-3, MMP-9, MMP-10, and MMP-13 and that of their tissue inhibitors TIMP-1 and TIMP-2 in colon cancer cells using real-time QRT-PCR assay was determined." (PMID 22415590, 2012). "In our studies, we observed that overexpression of claudin-1 in colon cancer cells increased activity of both MMP-2 and MMP-9 while inhibition of claudin-1 resulted in a significant decrease in MMP-9 activity." (PMID 20671913, 2010). "Two major matrix metalloproteinases (MMPs) in colon cancer, MMP-2 and MMP-9, were then studied using gelatin zymography." (PMID 19603013, 2009). "In a murine model, AB0041, an antibody with highly specific noncompetitive MMP-9 inhibitory profile, effectively reduced colon cancer xenograft growth and metastasis." (PMID 40332093, 2025). "Consistent with our previous reports, we also found that the 18‐amino acid N‐terminal tail domain of H3 is removed by MMP‐9 in colon cancer cells, suggesting a conserved specificity of MMP‐9 among different cell types." (PMID 38600695, 2024). "Along with our demonstration of the causal role that MMP‐9‐dependent H3NT proteolysis plays in activating a cluster of growth‐stimulatory gene in colon cancer cells, our ChIPac‐qPCR analysis indicated that H3NT proteolysis in the promoter region of target genes correlates with MMP‐9 transactivation." (PMID 38600695, 2024). "Nevertheless, research has indicated that the mRNA, protein, and/or activity levels of two specific MMPs, MMP-2 and MMP-9, are significantly upregulated in CRC tissues (even 10-fold within the invasive regions of colon cancer specimens) compared to normal colonic mucosa." (PMID 39683504, 2024). "Furthermore, the downregulation of MMP-2 and MMP-9 by inhibiting ERK and NF-κB activity reduces colon cancer cell migration and invasion." (PMID 38438872, 2024). "Furthermore, luteolin inhibits MMP9 in vitro and decreases the expression of MMP9 and MMP2 in a mouse model of colon carcinoma." (PMID 37237945, 2023). "In our study, ADAP1‐NOC4L overexpression increased cell motility and invasiveness, which was in the same way as MMP9, BCL2 expression, and BAX downregulation and thus could be inferred to be effective in colon carcinoma cell metastasis." (PMID 35702822, 2023). "We therefore detected the changes in such protein expressions in colon cancer cells (i.e., knockdown of PCSK9 expression significantly upregulated level of E-cadherin protein), but downregulated expressions of N-cadherin, MMP9, and Snail 1 proteins in HCT116 and HT-29 cells." (PMID 36242053, 2022). "In addition, in colon cancer cells, AKT2-HK2-NF-κB/HIF1α/MMP2/MMP9 axis increased the invasion, tumorigenesis, and metastasis of in vitro and promotes lung metastasis in nude mice in vivo." (PMID 35953860, 2022). "Therefore, the potential treatment of Ca and Cal alone and combination with LPS stimulated HCT116 colon cancer cell lines were assessed for the expression of the MMP-2 and MMP-9 functions and Cal- and CA-treated cells." (PMID 36235161, 2022). "Herein, we noticed that CA with Cal treatment could suppress MMP-2 and MMP-9 protein expression in HCT116 cell lines, which demonstrates that combinatorial treatment can be an anti-metastatic agent in colon cancer cells." (PMID 36235161, 2022). "The enzymatic activities of MMP2 and MMP9 were evaluated by zymography in a cohort of 26 surgical colon cancer tissues paired with non-tumoral adjacent tissue." (PMID 34830271, 2021).
colon carcinoma (continued). "Moreover, Endostar, a recombinant human endostatin, significantly inhibited the metastasis of colon cancer by reducing the phosphorylation of AKT and ERK, and inhibiting the expression of MMP-2 and MMP-9 protein." (PMID 34654351, 2021). "In vitro studies showed that the MMPI successfully inhibited MMP-9 activity in a dose-dependent manner in colon cancer cells, with an IC50 of 10 μg·mL−1 without impairing gene expression nor cell growth." (PMID 34948082, 2021). "RUNX3 can inhibit the invasion and metastasis of human colon cancer HT-29 cells, and the mechanism may be related to decreased expression of MMP-2 and MMP-9." (PMID 32184893, 2020). "MMP9 is known to process latent TGFβ into its active form, and TGFβ was recently shown to be part of the immune‐suppressive TME in colon tumors." (PMID 31793740, 2020). "Finally, FABP4 overexpression improved EMT progression of colon cancer, as evidenced by the upregulation of Snail, MMP-2 and MMP-9, the downregulation of E-cadherin." (PMID 33088219, 2020). "Meanwhile, in the presence of MMP-9 antibody, the number of invasive cells decreased, suggesting that MMP-9 induced by CA might play an important role in colon cancer cell invasiveness." (PMID 32408577, 2020). "The TANKs in patients with colon cancer also express MMP2, MMP9, and TIMP, as shared features with dNK cells which could be relevant to the invasive capabilities and proangiogenic functions of colorectal cancer-NK cells." (PMID 31057536, 2019). "Cytolytic-high colon tumors on the other hand, were characterized by recurrent deletions at loci 1p35.3 (PIK3CD, TP73, miR34a), 6p25.3 (FOXC1), and 21q11.1 (Let-7c), and amplifications at loci 8q24.21 (MYC) and 20q13.12 (MMP9)." (PMID 31429779, 2019). "Furthermore, this down-regulation of REV3L also diminished colon cancer cell migration, and down-regulated MMP-2 and MMP-9." (PMID 29435169, 2018). "Furthermore, we showed that DC-SIGNR promoted the liver metastasis of colon cancer cells through a novel regulatory pathway in which DC-SIGNR notably increased the expression of metallothionein isoforms and MMP9." (PMID 28109307, 2017). "In other cell systems, p38 MAPK mediates MMP-9 upregulation in response to several stimuli, including TNF-α and SDF-1/CXCR7 in bladder and ovarian, respectively, carcinoma cells, and clusterin/thrombospondin-1 in platelet-stimulated colon cancer." (PMID 27829220, 2016). "Both MMP9 and MMP2 are required for promotion of liver metastasis of colon cancer in a mouse model To identify the cell type(s) that produce these matrix metalloproteinases, we performed quantitative RT-PCR analyses on the sorted myeloid cells isolated from the liver metastatic foci." (PMID 25326065, 2014). "These inhibitory effects were accompanied by mechanistic down-regulation of the protein levels of cyclooxygenase-2 (COX-2), matrix metallopeptidase-9 (MMP-9), vascular endothelial growth factor (VEGF), and cyclin D1, as well as by the induction of apoptosis in colon tumors." (PMID 25389774, 2014). "Importantly, when MMP‐9 E402A catalytic dead mutant was expressed in MMP‐9‐depleted cells, target genes were still expressed at very low levels, underscoring the importance of MMP‐9‐dependent H3NT proteolysis for target gene activation in colon cancer cells." (PMID 38600695, 2024). "The involvement of MMP‐9‐dependent H3NT proteolysis in promoting the growth capacity of colon cancer cells was also confirmed by similar colony formation and MTT assays showing a substantial decrease in the growth rate of SW620 cells after treatment with MMP‐9 inhibitor MMP9‐I." (PMID 38600695, 2024). "Moreover, intestinal stents inhibited the expression of MMP-9 and COX-2 in colon tumors." (PMID 38535948, 2024).
colon carcinoma (continued). "In the subsequent in vitro experiments, after LEMD1 was depleted, the proliferation of colon cancer cells was observably impeded, as accompanied with the declined protein levels of proliferation markers Ki-67 and PCNA and invasion- and migration-related factors MMP2 and MMP9." (PMID 35294319, 2022). "However, MMP9, MMP12 and TIMP3 proteins were increased in colon cancer cells." (PMID 32171282, 2020). "Moreover, our study demonstrated that knockdown of FXR in colon cancer cells induced EMT, accompanied by upregulation of Snail, Slug, vimentin, fibronectin, and MMP-9, and downregulation of E-cadherin and ZO-1, whereas ectopic expression of FXR had reversed change." (PMID 32807788, 2020). "In addition, in colon cancer, andrographolide represses cell proliferation, elevates cell apoptosis, and activates caspase-3/9 in SW620 human colon cancer cells by inhibiting NF-κB, TLR4, MyD88, and MMP-9 signaling activation." (PMID 31242947, 2019). "In addition, the fermentation supernatants of the L. delbrueckii strain were found to decrease MMP-9 activity in SW620 cells, which may prevent the invasion of colon cancer cells." (PMID 24765211, 2014). "Furthermore, kaempferol may play an anti-colon cancer role by regulating the expression of MMP1, MMP2, and MMP9 protein, thereby increasing the expression level of miR-339-5p to mediate PKM alternative splicing reversing aerobic glycolysis in colon cancer cells." (PMID 39221164, 2024). "Also, levels of MMP-9 were measured in stool samples from 125 colon cancer patients and showed that MMP-9 may be a promising noninvasive marker of CRC." (PMID 34502094, 2021). "Importantly, MMP‐9 knockdown and inhibition are well tolerated with no body weight loss observed in the SW620 xenograft model, suggesting that they may be useful for effective colon cancer therapy." (PMID 38600695, 2024). "In that study, MMP-9 and TIMP-1 also correlated with tumor stage, but no data were presented on survival nor, in contrast with our results, did patients with colon cancer have higher levels of MMP-9 than did rectal cancer patients." (PMID 29929486, 2018). "We used stably transfected colon carcinoma human cell line HCT116 with and without MMP9 without γ-radiation." (PMID 27861153, 2017). "We have not proven that apigenin and naringenin could exert anti-colon cancer effects via regulating PTGS2 and MMP9 with additional experiments in this study." (PMID 35847793, 2022). "Therefore, we next determined levels of endogenous miR-21 and ECM mediators in colon cancer cell line LS174 by RT-qPCR, and found a positive correlation between miR-21 and ECM mediators MMP-2, MMP-9, and MMP-11, but not between miR-21 and ECM inhibitor TIMP-2." (PMID 32427870, 2020). "The expression of MMP8 and MMP9, however, were not markedly changed following modulation of SREBP1, suggesting that MMP8 and MMP9 expression is not regulated by SREBP1 in colon cancer cells." (PMID 31299935, 2019). "We found that knockdown of LEF1 expression suppressed MMP2 and MMP-9 expression, but not MMP-7, indicating that the selective modulation of MMPs by LEF1 could have the biological significance in colon cancer progression." (PMID 24098538, 2013). "Moreover, knockdown of LEF1 expression could significantly decrease the levels of MMP-2 and MMP-9 protein, but not MMP-7 protein in shLEF1 cells compared to that of shNC colon cancer cells." (PMID 24098538, 2013).
ischemic stroke (250 papers, 2006 to 2026). A stroke disorder caused by obstruction of blood flow to the brain, due to thrombotic (local blood clot formation) or embolic (due to a blood clot or other material traveling from another site) event. "Disruption of the blood–brain barrier (BBB) is a key event leading to secondary brain damage, and elevated MMP-9 concentrations have been found to be associated with this process after ischemic stroke." (PMID 41503448, 2026). "Combination of GDF-15, aCL, aPS and MMP-9 substantially improved the risk prediction of depression at 3 months after ischemic stroke." (PMID 40529498, 2025). "Recent clinical studies have linked MMP-9 expression in the blood with infarct growth and hemorrhagic transformation after ischemic stroke." (PMID 39273389, 2024). "We report that MMP-2 levels were decreased in the brain tissue and plasma of our choline-deficient-diet male offspring following ischemic stroke, whereas MMP-9 levels were unaffected in the treatment groups." (PMID 39273042, 2024). "Higher levels of MMP-9 in patients with ischemic stroke are associated with severe brain edema and hemorrhagic transformation and predict bleeding after tissue plasminogen activator (t-PA) treatment." (PMID 39766566, 2024). "In aged mice subjected to ischemic stroke, adropin markedly decreased infarct volume and brain edema and improved both sensorimotor and cognitive functions, with effects linked to reduced MMP-9 activity and preservation of tight junction proteins." (PMID 39766320, 2024). "MMP-9 has been previously associated in adult ischemic stroke severity, lesion volume, and hemorrhagic conversion." (PMID 38734737, 2024). "Elevated levels of serum matrix metalloproteinase‐9 (MMP‐9) during the acute phase of ischemic stroke are indicative of an augmented risk for mortality and significant disability." (PMID 38376013, 2024). "TLR4 affects BBB degradation by regulating COX‐2 and MMP‐9, which are implicated in the pathology of ischemic stroke." (PMID 37452512, 2023). "The increase in the bloodstream of MMP-9 seems to be associated with the haemorrhagic transformation of an ischemic stroke." (PMID 37511304, 2023). "Meta-analyses conducted later showed a significant relationship between the MMP-9-1562C/T polymorphism and a risk of ischemic stroke." (PMID 37206663, 2023). "In ischemic stroke, MMP‐9 is associated with BBB degradation and inflammation, with higher levels of MMP‐9 predicting poor outcomes." (PMID 37452512, 2023). "Elevated MMP‐9 levels after ischemic stroke and low levels of MMP‐9 on admission are associated with better NIHSS scores." (PMID 37452512, 2023). "Another study in the Chinese population confirmed that the CC genotype of the MMP-9-1562C/T polymorphism was associated with a higher risk of the ischemic stroke, when compared to the TT genotype [OR (95%CI) = 5.47 (2.64–12.38)]." (PMID 37206663, 2023). "A higher serum MMP-9 level in ischemic stroke was associated with an increased risk of physical disability (mRS) in a 3-month follow-up study." (PMID 36699006, 2022). "Unexpectedly, we did not detect significant changes in other preset biomarkers, such as MMP-9 and ferritin, which were previously reported to be associated with post-thrombolytic hemorrhagic transformation in ischemic stroke." (PMID 35720096, 2022). "Ischemic stroke-induced BBB damage also increases the activation of matrix metalloproteinase-9 (MMP-9), which is associated with tight junction components, resulting in a disruption of BBB integrity." (PMID 36358564, 2022). "Ginsenoside Rb1 protects loss of BBB integrity in ischemic stroke by suppressing neuroinflammation induction of matrix metalloproteinase-9 (MMP-9) and nicotinamide adenine dinucleotide phosphate oxidase 4 (NOX4)-derived free radical." (PMID 35721176, 2022).